SPDEF (SAM pointed domain containing ETS transcription factor)
Diseases named in the same sentence as SPDEF in open-access papers (continued):
Sharing a sentence is not in itself a finding about the gene and the disease.
lung cancer (14 papers, 2008 to 2023). A malignant neoplasm involving the lung. "Next, we sought to determine whether FOXA3 or SPDEF recapitulates the in vivo function in human lung cancer cells that harbor a KRAS mutation." (PMID 28255028, 2017). "SPDEF was proved to act as a tumor-promoter in hepatocellular and lung cancers by maintaining the self-renewal of CSCs." (PMID 37633945, 2023). "FOXA3 and SPDEF induce MUC5AC and MUC5B, while HNF4A induces MUC3 in human lung cancer cells harboring a KRAS mutation." (PMID 36860703, 2022). "To further investigate the role of TOX3 and SPDEF expression in cancer progression, we performed a survival curve analysis to evaluate the effects of gene expression in lung cancer patients with lung adenocarcinoma." (PMID 29285217, 2017). "Here, we show that the NPTNβ-SPDEF-mediated induction of solute carrier family 22 member 18 antisense (SLC22A18AS) is definitely required for the epithelial-mesenchymal transition (EMT) through the NPTNβ pathway in lung cancer cells." (PMID 32490214, 2020). "Moreover, our data demonstrate that there was hypomethylation of CpG number 6 in the SPDEF promoter in the COPD-derived ALI cultures, which is in line with the over-expression and hypomethylation of SPDEF in lung cancer." (PMID 28450970, 2017). "However, it remained to be addressed how an S100A8/A9-NPTNβ signal that led to SPDEF activation might control the upregulation of lung cancer dissemination." (PMID 32490214, 2020). "Other studies showed that aberrant DNA methylation was associated with dysregulation of SPDEF and FOXA2 expression in lung cancer, although DNA methylation regulation of SPDEF and FOXA2 expression has not been assessed in lung tissue of patients with COPD." (PMID 28450970, 2017). "However, it is unknown whether SPDEF directly binds to the loci of MUC5AC and/or MUC5B in lung carcinoma cells." (PMID 28255028, 2017). "SPDEF plays a vital role in NPTNβ functions and the NPTNβ–SPDEF-induced solute carrier family 22 member 18 antisense (SLC22A18AS) is essential for EMT and cellular motility in lung cancer, with a negative correlation with overall survival of patients." (PMID 37701037, 2023).
asthma (10 papers, 2010 to 2025). "Therefore, dysregulation of SPDEF expression by RPS4Y1 may predispose male children to asthma development." (PMID 40649992, 2025). "SPDEF is well-known to be increased in airway epithelial cells of asthma patients, inducing goblet cell metaplasia and increasing mucous production." (PMID 40649992, 2025). "Other markers previously associated with type 2 inflammation in asthma, including CLCA1, SERPINB2, and SPDEF, were significantly (p < 0.0001) increased in the IL-13 treated HBEC compared to normal HBEC." (PMID 38706568, 2024). "Additionally, SAM pointed domain containing ETS transcription factor (SPDEF) demonstrated increased activity in human club cells, highlighting the complex transcriptional landscape of asthma." (PMID 39391497, 2024). "Although distinct endotypes (Th2-High and Th2-Low) have been described in asthma, we focus here on the importance of the IL-13/SPDEF/STAT6 pathway (interleukin-13/SAM pointed domain-containing ETS transcription factor/signal transducer and activator of transcription 6)." (PMID 35269434, 2022). "Linked to increased mucus production are SPDEF (SAM pointed domain-containing Ets transcription factor) and CLCA1, both also induced by T2 cytokines in the airway epithelium and the latter is also linked genetically to asthma and part of the epithelial T2 signature introduced above." (PMID 33255348, 2020). "In contrast to these reports, our study was done in animals with induced asthma, which leads to goblet cell metaplasia and upregulation of TMEM16A and a number of proinflammatory proteins, including SPDEF." (PMID 34360618, 2021). "Second, and similarly to asthma, COPD patients display goblet cell hyperplasia (in large airways) and metaplasia (in small airways, where virtually no goblet cells are found in healthy subjects), a feature that is driven by the transcription factors SPDEF and FOXA3." (PMID 34248677, 2021).
colon cancer (9 papers, 2014 to 2021). "Both, reduced expression of SPDEF in prostate, breast, ovarian and colon tumors, and increased SPDEF in breast, ovarian and prostate tumors has been reported." (PMID 25254494, 2014). "Further, SPDEF inhibited the expression of β-catenin-target genes in mouse colon tumors, and interacted with β-catenin to block its transcriptional activity in colorectal cancer cell lines, resulting in lower levels of cyclin D1 and c-MYC." (PMID 24472151, 2014). "A previous study found that expression of SPINK4 was decreased in colon cancer cells when SPDEF was inhibited and resulted in terminal differentiation and maturation of intestinal goblet cells, suggesting that SPINK4 was involved in the pathogenesis of colon cancer." (PMID 30976466, 2019).
gastric cancer (8 papers, 2020 to 2025). A primary or metastatic malignant neoplasm involving the stomach. "Similar to this study, previous research has shown that SPDEF has a positive regulatory effect on the proliferation of gastric cancer cells." (PMID 34350121, 2021). "Another ETS family member, SAM, pointed domain containing ETS transcription factor (SPDEF) promotes the expression of transcription factor Forkhead Box M1 (FOXM1) by directly binding its promoter, which contains a core GGAT sequence, in gastric cancer cells." (PMID 41425714, 2025).
prostate tumors (8 papers, 2010 to 2025). "Since SPDEF inhibits cell migration, at least in part, through MMP9 and MM13, increased expression of these MMP genes can contribute to Foxm1-mediated rescue of cell migration in SPDEF-deficient prostate tumor cells." (PMID 25254494, 2014). "The role of SPDEF as a co-activator that induces the expression of prostate-specific antigen (PSA) in LNCaP prostate tumors has been established." (PMID 40457266, 2025). "In prostate, SPDEF directly interacts with the androgen receptor functioning as a co-activator to induce prostate-specific antigen (PSA) in LNCaP prostate tumor cells." (PMID 25254494, 2014). "We found inverse correlations between SPDEF and the Foxm1 oncogene in both mouse and human prostate tumors and demonstrated that SPDEF inhibits tumor cells proliferation through Foxm1 oncogene." (PMID 25254494, 2014). "Altogether, SPDEF inhibits prostate carcinogenesis by preventing Foxm1-regulated proliferation of prostate tumor cells." (PMID 25254494, 2014). "Since SPDEF expression inversely correlated with Foxm1 expression in mouse and human prostate tumors, we examined the possibility that SPDEF directly represses the Foxm1 promoter." (PMID 25254494, 2014). "Previous studies demonstrated that SPDEF is expressed in normal prostate epithelium and prostate tumors in mice and human patients; however, its role in prostate carcinogenesis is still controversial." (PMID 25254494, 2014). "ETS-4 is closely related to the human ETS protein SPDEF that exhibits aberrant expression in breast and prostate tumors." (PMID 20862312, 2010). "Cell lines from breast and prostate tumors have altered SPDEF expression, although the significance of this misregulation remains controversial." (PMID 20862312, 2010). "The number of PH3-positive cells in TRAMP/SPDEF OE prostate tumors was reduced by 60%." (PMID 25254494, 2014). "The mRNA levels of SPDEF are altered in breast and prostate tumors." (PMID 20862312, 2010). "The enhanced expression of SPDEF could be due to its genetic alterations in prostate tumors." (PMID 32680982, 2020). "Thus, the loss of SPDEF was not sufficient to initiate prostate tumors; however SPDEF deficiency promoted prostate carcinogenesis in the TRAMP mouse model." (PMID 25254494, 2014). "ADT reduces a transcriptional repressor (SAM pointed domain-containing ETS transcription factor, SPDEF) of CCL2, which mediates EMT of prostate tumor cells." (PMID 34199763, 2021). "Consistent with findings in the transgenic mice, expression of SPDEF in TRAMP C2 cells decreased Foxm1 mRNA and protein expression in orthotopic prostate tumors." (PMID 25254494, 2014). "The EPI measures the mRNA copy number of three genes, ERG, PCA3, and SPDEF, in the exosomes of prostate tumor cells released into the urine without DRE." (PMID 39081487, 2024). "In the absence of TRAMP transgene, SPDEF−/− mice did not develop prostate tumors or PINs, and expression of proliferation-specific genes in SPDEF−/− prostates was unchanged." (PMID 25254494, 2014). "Expression of SPDEF reduced the tumor burden, decreased the number of Ki67 and PH3-positive cells, and reduced mRNA levels of proliferation-specific genes Cdc25b, Cyclin B1, Cyclin A2, PLK1, CKS1, Aurora B and Topo2 alpha in the prostate tumors." (PMID 25254494, 2014). "SPDEF was originally discovered as a transcription factor that directly interacts with androgen receptor and functions as its co-activator to induce expression of prostate specific antigen (PSA) in LNCaP prostate tumor cells." (PMID 25254494, 2014).
breast tumor (6 papers, 2010 to 2023). "SPDEF belongs to the Ets family of transcription factors that is expressed in luminal, apocrine, and ErbB2-positive breast tumors and is associated with poor prognosis." (PMID 28915724, 2017). "The top eight genes that negatively correlated to POLR3G expression (MLPH, FOXA1, SPDEF, AR, SIDT1, AGRP2, XBP1, GATA3) are typically overexpressed in ER+ breast tumors as compared to ER- breast tumors." (PMID 36497214, 2022). "In addition, the expression of ALDH1A1, the most widely used cell surface marker for isolating breast tumor-initiating cells, known as cancer stem cells, was also higher in MCF7 and BT-474 cells with over-expressed SPDEF compared to control group." (PMID 37633945, 2023).
colorectal cancer (6 papers, 2014 to 2024). A primary or metastatic malignant neoplasm that affects the colon or rectum. "In studies of mouse and human colorectal cancer, SPDEF induces a quiescent state of cancer cells by disrupting the binding of β-catenin to TCF1 and TCF3 and by regulating genes that control the cell cycle." (PMID 36809297, 2023).
ovarian carcinoma (6 papers, 2007 to 2025). A malignant neoplasm originating from the surface ovarian epithelium. "Initially, SPDEF mRNA and protein was reported to be overexpressed in ovarian cancer (OC), particularly serous epithelial ovarian tumours." (PMID 30200227, 2018). "Several groups reported the increased expression of SPDEF during progression of prostate, breast and ovarian cancers, suggesting the oncogenic role of SPDEF." (PMID 25254494, 2014). "The functional role of SPDEF in progression of several cancers has been investigated, including CRC, HCC, bladder, prostate and ovarian cancer." (PMID 30200227, 2018).
dry eye (3 papers, 2017 to 2025). "We measured the goblet cell marker SPDEF to evaluate dry eye and found an increase in SPDEF mRNA expression levels at one week post-treatment." (PMID 40861543, 2025). "In this study, we investigated the utility of the ocular surface test, which clinically evaluates mucin-related gene (SPDEF, MUC5AC, and MUC16) expression levels on the ocular surface in patients with dry eye." (PMID 33232357, 2020).
hepatocellular carcinoma (3 papers, 2021 to 2023). A malignant tumor that arises from hepatocytes. "Similarly, SPDEF-mediated microRNA-448 activation is also involved in the oncogenicity and self-renewal of hepatocellular carcinoma stem cells." (PMID 36809297, 2023). "A recent study reported that SPDEF could bind to the miR-448 promoter to downregulate DOT1L, whereby promoting self-renewal of hepatocellular carcinoma stem cells." (PMID 37633945, 2023).
pancreatic cancer (3 papers, 2021 to 2024). "Pancreatic cancer patients with diminished SPDEF expression exhibited significantly enhanced OS (P ═ 0.0024) and RFS (P ═ 0.011)." (PMID 38520747, 2024). "Initiating our investigation, we employed a bioinformatics approach to identify SPDEF as a significant regulator within the complex landscape of pancreatic cancer." (PMID 38520747, 2024). "Through qRT-PCR and WB analytical methodologies, we ascertained a significant upregulation of SPDEF in pancreatic cancer cells, predominantly within PANC-1 and MIA PaCa-2 lines, designating them for further experimental exploration." (PMID 38520747, 2024). "Unveiling the role of novel molecules, such as SPDEF, in the complex molecular landscape of pancreatic cancer may be pivotal for crafting innovative therapeutic avenues." (PMID 38520747, 2024).
adenoma (2 papers, 2014 to 2018). A neoplasm arising from the epithelium. "In colorectal tumors from patients, loss of SPDEF was observed in approximately 85% of tumors and correlated with progression from normal tissue, to adenoma, to adenocarcinoma." (PMID 24472151, 2014).
bladder cancer (2 papers, 2018 to 2019). "SPDEF mRNA and protein expression is decreased in bladder cancer, particularly in high grade tumours, and re-expression of SPDEF in bladder cancer cell lines inhibited proliferation and invasion in vitro, and reduced xenograft growth in vivo." (PMID 30200227, 2018).
endometrial cancer (2 papers, 2018 to 2024). Primary or metastatic malignant neoplasm involving the endometrium (mucous membrane that lines the endometrial cavity). "Other estrogen-responsive genes upregulated in CTCF-altered cancers, namely SPDEF, TFF3 and PIGR, are also components of these gene signatures, indicating that loss of CTCF could be an important factor determining endometrial cancer progression and pathology." (PMID 30513694, 2018). "Furthermore, the expression of estrogen-responsive genes KIAA1324, MLPH, MSX2, SPDEF, TFF3, and PIGR were all significantly up-regulated in CTCF-altered endometrial cancers (p = 0.0004, 0.0007, 0.0032, 0.0009, 0.0122, and 0.0028 respectively)." (PMID 30513694, 2018).
lung disease (2 papers, 2012 to 2019). "The role of SPDEF in mucous cell metaplasia is well attended in the study of lung diseases." (PMID 22518155, 2012).
melanoma (2 papers, 2020 to 2022). A malignant, usually aggressive tumor composed of atypical, neoplastic melanocytes. "In addition, no studies have reported on the expression and function of ELK3, ETV5 ELF3, ELF5, ETS2, and SPDEF in melanoma." (PMID 33424867, 2020). "In particular, ELK3, ETS1, ETV1, ETV4, ETV5, and SPI1 were significantly upregulated in melanoma, whereas EHF, ELF3, ELF5, ERG, ETS2, ETV7, and SPDEF were significantly downregulated in the tumor." (PMID 33424867, 2020).
mucinous adenocarcinoma (2 papers, 2022 to 2023). An invasive adenocarcinoma composed of malignant glandular cells which contain intracytoplasmic mucin. "A gene signature of invasive mucinous adenocarcinoma of the lung, which includes transcription factors (FOXA3, SPDEF, and HNF4A) and mucin proteins (MUC5AC, MUC5B, and MUC3) has been identified." (PMID 36860703, 2022). "Additionally, markers of invasive mucinous adenocarcinoma (MUC5AC, MUC5B, SPDEF, FOXA3) were highly expressed in organoids, retaining the histological characteristics of the patient’s original tumor." (PMID 37508518, 2023).
Obesity (2 papers, 2018 to 2019). Accumulation of substantial excess body fat. "NUDT3, SPDEF, and PACSIN1 have been identified in a closely linked region that is associated with obesity or carcass traits, such as body growth and size, in human or pigs." (PMID 31188900, 2019). "Instead, our screen suggests that different nearby cis gene may be more fruitful for further functional follow up for obesity, namely ZCCHC8, VPS33A, RSRC2; SPDEF, NUDT3; SETD1, VKORC1; SGSM2, SRR; VASP, SIX5; OTX1; BANK1; ARIH1; ELL; CHST8, respectively." (PMID 29608557, 2018).
prostate adenocarcinoma (2 papers, 2014 to 2020). "Thus, SPDEF may function as a tumor suppressor in prostate adenocarcinoma cells." (PMID 25254494, 2014). "Since TRAMP C2 prostate adenocarcinoma cells do not express endogenous SPDEF, we used SPDEF lentivirus to generate TRAMP C2 cells with the stable over-expression of SPDEF (SPDEF OE)." (PMID 25254494, 2014).
atopic dermatitis (1 paper, 2025). "We have reported that the expression level of SPDEF mRNA, a differentiation marker of goblet cells, correlates with MUC5AC mRNA in ocular surface tests of patients with atopic dermatitis." (PMID 40861543, 2025).
benign prostatic hyperplasia (1 paper, 2025). A non-cancerous nodular enlargement of the prostate gland. "This study aimed to evaluate the methylation status of a specific CpG dinucleotide within the SPDEF (SAM-pointed domain-containing ETS transcription factor) gene promoter in blood leukocytes of PCa patients, using benign prostatic hyperplasia (BPH) samples as a control group." (PMID 40457266, 2025). "To investigate the potential role of the SPDEF gene in PCa, we assessed the methylation status of SPDEF in 360 peripheral blood samples (180 PCa and 180 benign prostatic hyperplasia [BPH] controls) using methylation-sensitive restriction enzyme PCR (MSRE-PCR) and quantitative PCR (qPCR)." (PMID 40457266, 2025).
cervical cancer (1 paper, 2019). A primary or metastatic malignant neoplasm involving the cervix. "The mean levels of CNOT7, PAX5, and SPDEF are slightly elevated in CESC samples compared with those in healthy tissue, though not significantly, while the level of TGM2 is significantly downregulated in cervical cancer." (PMID 30918060, 2019).
COVID-19 (1 paper, 2023). A disease caused by infection with severe acute respiratory syndrome coronavirus 2. "For example, compared to activated STAT2 and KLF5 in mild/moderate goblet cells, SPDEF, ELF3, XBP1, and NR2F6 were found activated in patients with severe COVID-19." (PMID 37936693, 2023). "In summary, SPDEF and ELF3 were shared between goblet and squamous cells in severe COVID-19, and S100A9 was co-upregulated." (PMID 37936693, 2023). "In goblet cells, STAT2 and KLF5 were highly activated and upregulated in many genes with mild/moderate COVID-19, such as ISGs (PARP14 and IFI44L), whereas ELF3, SBP1, NR2F6, and SPDEF were preferentially activated in severe COVID-19 to regulate the expression of their targets." (PMID 37936693, 2023). "Furthermore, NR2F6, SPDEF, and ELF3 were found to be activated in squamous cells in patients with severe COVID-19, and this activity was also shared with goblet cells." (PMID 37936693, 2023). "Similarly, SPDEF and ELF3 were found to be activated in squamous cells, and CEBPD and FOS were shared between CD14 and CD14 monocytes in severe COVID-19." (PMID 37936693, 2023). "For squamous cells, there were no activated regulons in SPDEF and ELF3 in mild/moderate COVID-19, but they were activated in severe COVID-19." (PMID 37936693, 2023). "For example, RFX2 and RFX3 showed high activity in ciliated cells regardless of disease severity, while XBP1, NR2F6, SPDEF, and ELF3 were preferentially activated in goblet cells in patients with severe COVID-19, and KLF5 and STAT2 were coactivated in patients with mild/moderate COVID-19." (PMID 37936693, 2023).
fungal keratitis (1 paper, 2022). "Therefore, the upregulated expression of SPDEF and MARCO in murine fungal keratitis and their related properties may serve as potential therapeutic targets in fungal keratitis." (PMID 35743555, 2022).